UBA1 (ubiquitin like modifier activating enzyme 1)
Diseases named in the same sentence as UBA1 in open-access papers (continued):
Sharing a sentence is not in itself a finding about the gene and the disease.
VEXAS syndrome (continued). "Subsequent NGS examination identified a mutation in the EZH2 gene with unclear significance and a UBA1 mutation, leading to a diagnosis of very low-risk MDS (IPSS-R of 1) and VEXAS syndrome." (PMID 38398362, 2024). "Next-generation sequencing (NGS) detected mutations in DNMT3A and UBA1, leading to a diagnosis of low-risk MDS (IPSS-R of 2) and VEXAS syndrome." (PMID 38398362, 2024). "Given his atypical course, negative PR3 ELISA and lack of evidence of GPA on renal biopsy, an alternate diagnosis of VEXAS syndrome was considered; NGS from peripheral blood was positive for a p.Met41Thr mutation in UBA1." (PMID 39411287, 2024). "After the description of VEXAS syndrome in 2020, we retrospectively sequenced DNA from initial diagnosis by next-generation sequencing (NGS) and identified an UBA1 (c.118-1G > C) mutation." (PMID 38214707, 2024). "NGS testing revealed mutations in TET2, U2AF1, and UBA1, leading to the diagnosis of low-risk MDS (IPSS-R of 2.5) and VEXAS syndrome." (PMID 38398362, 2024). "Given the suspicion of VEXAS syndrome, UBA1 genetic analysis was carried out in 2021, which detected the p.Met41Thr mutation." (PMID 39251478, 2024). "UBA1 is a newly rediscovered gene in the field of hematology in the context of VEXAS syndrome, a prototypical hematoinflammatory disease." (PMID 36823397, 2023). "Decreased activity of the E1 ubiquitin-activating enzyme UBA1 can contribute to aging and diseases like Alzheimer’s and VEXAS syndrome." (PMID 37558718, 2023). "Interrogation of the 100kGP dataset, which includes whole genomes of participants recruited for either rare diseases or cancer, similarly identified only one case with the known pathogenic UBA1 variant c.121A>C, p.Met41Leu (variant allele frequency [VAF]: 8%), associated with VEXAS syndrome." (PMID 40415210, 2026). "VEXAS syndrome is an adult-onset autoinflammatory disorder caused by somatic UBA1 variants, but there are no standardized criteria for genetic testing or diagnostics." (PMID 41026267, 2025). "Together, these findings establish a novel human model of VEXAS syndrome, identify key roles for UBA1 and UBA6 in disease pathogenesis, and demonstrate that UBA6 inhibition represents a promising therapeutic strategy for selectively targeting UBA1 mutant clones." (PMID 40588566, 2025). "In VEXAS syndrome UBA1, which catalyzes a crucial step in the ubiquitination process, is functionally impaired which by accumulation of proteins might lead to activation of unfolded protein response and inflammatory response." (PMID 40119917, 2025). "One therapeutic strategy for VEXAS syndrome is to control hyperinflammation and UBA1 mutant clones." (PMID 40498270, 2025). "Three disorders are associated with pathogenic variants of the UBA1 gene: vacuoles, E1 enzyme, X-linked, autoinflammatory, somatic (VEXAS) syndrome, lung cancer in never smokers (LCINS), and X-linked spinal muscular atrophy (XL-SMA, SMAX2)." (PMID 39762237, 2025). "The diagnosis of VEXAS syndrome is based on the presence of pathogenic UBA1 mutations, rather than specific clinical manifestations." (PMID 40846800, 2025). "Notably, we identified UBA6 inhibition as a unique vulnerability in UBA1 mutant cells, offering a potential therapeutic strategy for VEXAS syndrome." (PMID 40588566, 2025). "At present, research on the immune regulation of UBA1 mainly focuses on VEXAS syndrome." (PMID 39183260, 2024). "This case series reports on the clinical presentation, laboratory findings, imaging characteristics, treatments, and outcomes of nonischemic cardiac manifestations in patients with VEXAS syndrome with confirmed pathogenic UBA1 alterations." (PMID 39666342, 2024). "Beyond VEXAS syndrome, distinct UBA1 mutations have been implicated in lung cancer in never smokers (LCINS) and spinal muscular atrophy (SMA)." (PMID 38360993, 2024).
VEXAS syndrome (continued). "Mutations in the ubiquitin-activating enzyme UBA1 cause autoinflammation (VEXAS syndrome), lung cancer in never-smokers (LCINS), and spinal muscular atrophy (SMA)." (PMID 38360993, 2024). "Whereas in VEXAS syndrome, UBA1 mutations alone are thought to drive both the inflammatory and MDS phenotypes, in UBA1‐wildtype patients with MDS/CMML, early somatic mutations in TET2/IDH1 (and/or SRSF2) are thought to contribute to the MDS/CMML and SIAD components." (PMID 39981058, 2024). "The UBA1 mutation in VEXAS syndrome is a somatic mutation, meaning that it is not present in all tissue cells." (PMID 37501758, 2023). "VEXAS syndrome patients express a de novo hypomorphic UBA1 isoform in the myeloid compartment." (PMID 36739287, 2023). "UBA1 can mark cellular proteins for degradation through the ubiquitin–proteasome system, which can lead to the development of various diseases including small-cell lung cancer and VEXAS syndrome." (PMID 38057879, 2023). "It was also demonstrated that UBA1 variants only occurred in hematopoietic cell populations that matured into myeloid cells, and were not seen in B or T lymphocytes in VEXAS syndrome." (PMID 35757758, 2022). "Molecular diagnosis of VEXAS syndrome is made by the sequencing of the UBA1 gene." (PMID 35885496, 2022). "By screening the UBA1 gene sequences derived from MDS patients with AD from our center, we identified one patient with a p.Met41Leu missense mutation in UBA1, who should have been diagnosed as MDS comorbid with VEXAS syndrome." (PMID 33741056, 2021). "However, not all patients with canonical UBA1 mutations were diagnosed with VEXAS syndrome, suggesting incomplete disease penetrance." (PMID 40415210, 2026). "VEXAS syndrome ('Vacuoles', 'E1 enzyme', 'X-linked', 'Autoinflammatory' and 'Somatic') is a rare autoinflammatory disorder caused by somatic mutations in the UBA1 (ubiquitin-like modifier-activating enzyme 1) gene whose treatment and prognosis remain poorly understood." (PMID 42136657, 2026). "Thus, by reactivating residual UBA1 activity, auranofin may improve proteostasis and mitigate the aberrant inflammatory cytokine milieu in VEXAS syndrome." (PMID 40791602, 2025). "Notably, we observed no somatic hotspot variants in UBA1, a gene underlying VEXAS syndrome characterized by autoimmune phenotypes as expected based on recently reported population prevalence of UBA1 mutations in the United States." (PMID 40305610, 2025). "However, recent data challenge this hypothesis by demonstrating that the establishment of a cell-extrinsic inflammatory milieu by UBA1-mutant clones relatively more harmful to wild-type than to mutant cells in VEXAS syndrome." (PMID 40791602, 2025). "VEXAS syndrome was suspected but NextGen sequencing of peripheral blood showed no UBA1 mutation." (PMID 40295291, 2025). "In VEXAS syndrome, dysregulation of UBA1 may drive dependency on the UBA6/FAT10 axis." (PMID 40588566, 2025). "A few cases of individuals with VEXAS syndrome without vacuoles in the BM precursors, which might be linked to a specific UBA1 mutation, have been described." (PMID 39421750, 2024). "Since the UBA1 mutation in VEXAS syndrome is a somatic mutation, not all myeloid cells have it." (PMID 38410307, 2024). "In a detailed review of diseases involving deregulation of the ubiquitin–proteasome system, Beck suggests that the development of substrate-specific activator molecules, such as UBA1 in VEXAS syndrome or targeting the proteasome, could be beneficial in the management of these complex diseases." (PMID 35885496, 2022). "Patients with MDS and AD who have characteristic vacuoles in myeloid and erythroid precursor cells should be screened for UBA1 mutation, these patients are likely to have VEXAS syndrome and unlikely to improve with immunosuppressive drugs and should be considered for other alternative therapies." (PMID 33741056, 2021).
VEXAS syndrome (continued). "Due to the presence of vacuolization, testing for the ubiquitin-like modifier activating enzyme 1 (UBA1) gene was conducted, yielding a positive result and confirming the diagnosis of VEXAS syndrome." (PMID 40041629, 2025). "The subsequent emergence of macrocytic anemia, despite the absence of bone marrow vacuolization, led to UBA1 sequencing, confirming VEXAS syndrome." (PMID 40448343, 2025). "Whilst there are no official diagnostic criteria for VEXAS syndrome, VEXAS is characterized by the co-existence of acquired inflammatory and hematological symptoms as well as the presence of vacuoles in hematopoietic stem and progenitor cells and somatic UBA1 mutations." (PMID 36823397, 2023). "However, MM on a background of VEXAS syndrome seems to be relatively rare, and it has not been elucidated whether UBA1 is the driver gene for plasma cell dyscrasia such as MM." (PMID 35757758, 2022).
myelodysplastic syndrome (23 papers, 2021 to 2026). A clonal hematopoietic disorder characterized by dysplasia and ineffective hematopoiesis in one or more of the hematopoietic cell lines. "Vacuoles, E1 enzyme, X-linked, autoinflammatory, somatic (VEXAS) syndrome is an autoinflammatory disease caused by somatic variants in the UBA1 gene that lead to severe systemic inflammation and myelodysplastic syndrome." (PMID 35769485, 2022). "Vacuoles, E1 enzyme, X-linked, autoinflammatory, somatic (VEXAS) syndrome is an inflammatory disorder caused by somatic UBA1 variants, which are sometimes associated with hematological disorders, including myelodysplastic syndrome (MDS)." (PMID 35757758, 2022). "The newly described VEXAS, associated with somatic UBA1 mutations, exhibits an overlap of clinical and/or biological pictures with auto inflammatory signs and myelodysplastic syndrome (MDS)." (PMID 34884286, 2021). "It is characterized by somatic mutations in the UBA1 gene, systemic inflammation, macrocytic anemia, cytopenias, and bone marrow vacuolization and frequently overlaps with Sweet's syndrome, relapsing polychondritis, and myelodysplastic syndrome (MDS)." (PMID 42200825, 2026). "In this report, we present a case of a male patient diagnosed with VEXAS‐associated myelodysplastic syndrome following the detection of a non‐canonical UBA1 p.Gly477Ala variant whose bone marrow biopsy revealed a conspicuous absence of cytoplasmic vacuolization in hematopoietic cells." (PMID 39415928, 2024). "Myelodysplastic syndrome (MDS) was present in 50% of cases, highlighting the pathogenic association between UBA1 somatic mutations and clonal hematopoiesis." (PMID 41409287, 2025). "Pathogenic UBA1 mutations result in an often-fatal hematologic and inflammatory symptoms, which can present with overlapping features of well-established clinical diagnoses such as myelodysplastic syndrome (MDS) and vasculitis." (PMID 38360993, 2024). "As concurrent haematological disease such as myelodysplastic syndrome (MDS) may occur with VEXAS, the presence of a somatic UBA1 mutation is now being detected in patients with longstanding diagnoses of MDS pre-existing the discovery of VEXAS." (PMID 39347920, 2024). "This includes azacitidine, currently approved for myelodysplastic neoplasms (MDS), novel UBA1 inhibitors being developed for a broad spectrum of cancers, Protein Kinase R-like Endoplasmic Reticulum Kinase (PERK) inhibitors, and auranofin, a long-established drug for rheumatoid arthritis." (PMID 39347709, 2024).
spinal muscular atrophy (18 papers, 2015 to 2025). A motor neuron disease that affect the muscles, and characterized by muscle weakness and atrophy resulting from progressive degeneration and irreversible loss of the anterior horn cells in the spinal cord (i.e., lower motor neurons) and the brain stem nuclei. "A rare hemizygous missense mutation that impairs UBA1 function causes X-linked infantile spinal muscular atrophy, and reduced UBA1 expression has been reported in Huntington’s disease." (PMID 40570956, 2025). "Previous studies have shown that missense mutations in UBA1 cause spinal muscular atrophy (SMA) and are associated with lung cancer in never smokers (LCINS) (Table EV2)." (PMID 38360993, 2024). "Pathogenic UBA1 variants result in a rare form of childhood motor neuron disease spinal muscular atrophy." (PMID 37220877, 2023). "For instance, the autosomal recessive neuromuscular disease spinal muscular atrophy (SMA) is caused by loss of survival motor neuron 1 (SMN1) protein accompanied by a downregulation of UBA1 expression." (PMID 37558718, 2023). "Altered Ub distribution has been observed in ALS models, and mutations in the key UPS regulator ubiquitin-like modifier activating enzyme 1 (UBA1) cause the juvenile motor neuron disease, spinal muscular atrophy (SMA)." (PMID 31200561, 2019). "UBA1 is a central regulator of proteostasis, and mutations in UBA1 cause the motor neuron disease spinal muscular atrophy." (PMID 31200561, 2019). "Total loss of UBA1 is lethal, while defects in UBA1 expression or activity contribute to the pathogenesis of several neurodegenerative disorders such as spinal muscular atrophy, Huntington's disease, Parkinson's disease, Alzheimer's disease, and amyotrophic lateral sclerosis." (PMID 32258175, 2020). "Notably, suppression of UBA1 activity in Schwann cells is linked to spinal muscular atrophy." (PMID 28798148, 2017). "Dysregulation of UBA1 induces neuromuscular pathology in animal models of spinal muscular atrophy and systemic restoration of UBA1 rescues this pathology." (PMID 37220877, 2023). "Specific disruption of UBA1 pathway is reported in in spinal muscular atrophy and Huntington's disease (HD), which was also enriched in our IPA study." (PMID 34527416, 2021). "A study on spinal muscular atrophy (SMA) showed that ubiquitin-like modification 1 (Uba1) and ubiquitin-dependent pathways play an important role in maintaining Schwann cell homeostasis and provide important additional experimental evidence." (PMID 30186571, 2018). "Dysregulation of UBA1/GARS pathways in spinal muscular atrophy mice disrupted sensory neuron fate, phenocopying GARS-dependent defects associated with Charcot-Marie-Tooth disease." (PMID 30239612, 2018). "We show that restoration of ubiquitin-like modifier-activating enzyme 1 (UBA1) was sufficient to correct sensory-motor connectivity in the spinal cord of mice with spinal muscular atrophy." (PMID 30239612, 2018). "Therapeutic targeting of ubiquitin pathways by restoring UBA1 levels is a safe and effective systemic treatment for spinal muscular atrophy." (PMID 27699224, 2016). "Critical contributions of UBA1-dependent pathways to the regulation of homeostasis and degeneration in the nervous system are emerging, including specific disruption of UBA1 in spinal muscular atrophy (SMA) and Huntington's disease (HD)." (PMID 26432019, 2015). "Dysregulation of UBA1/GARS pathways in spinal muscular atrophy mice disrupted sensory neuron fate." (PMID 39457418, 2024). "A similar E2 charging bottleneck exists in some lung cancer-associated UBA1 mutations, but not in spinal muscular atrophy-causing UBA1 mutations, which instead, render UBA1 thermolabile." (PMID 37873213, 2023).
spinal muscular atrophy (continued). "We conclude that defective sensory motor connectivity in spinal muscular atrophy results from perturbations in a UBA1/GARS pathway that modulates sensory neuron fate, thereby highlighting significant molecular and phenotypic overlap between spinal muscular atrophy and Charcot-Marie-Tooth disease." (PMID 30239612, 2018). "UBA1 may also play a role in more common SMN1-dependent spinal muscular atrophy." (PMID 39982357, 2025). "Sensory neuron fate was corrected following restoration of UBA1 expression and UBA1/GARS pathways in spinal muscular atrophy mice." (PMID 30239612, 2018).
Adult onset (11 papers, 2021 to 2026). Onset of disease manifestations in adulthood, defined here as at the age of 16 years or later. "Genetic testing for adult-onset autoinflammatory syndromes was performed and revealed UBA1 c,121 A > G p.(Met41Val) mutation." (PMID 39251478, 2024). "Vacuoles, E1 enzyme, X-linked, autoinflammatory, somatic syndrome (VEXAS) is an adult-onset autoinflammatory disease caused by somatic mutations in UBA1 (encoding ubiquitin-like modifier activating enzyme 1)." (PMID 38167209, 2024). "VEXAS (vacuoles, E1 enzyme, X-linked, autoinflammatory, somatic) syndrome, characterized by somatic mutations in UBA1 in HSCs, is associated with severe adult-onset autoinflammatory disease and hematologic neoplasms." (PMID 36013314, 2022). "VEXAS (Vacuoles, E1 Enzyme, X-linked, Autoinflammatory, Somatic) syndrome is a rare, adult-onset autoinflammatory disorder caused by somatic mutations in the UBA1 gene, most commonly affecting older men and associated with systemic inflammation and hematologic abnormalities." (PMID 41704985, 2026).
acute myeloid leukemia (10 papers, 2020 to 2024). Acute myeloid leukemia (AML) is a group of neoplasms arising from precursor cells committed to the myeloid cell-line differentiation. "Uba1 forms the first step in marking proteins with ubiquitin for proteasomal degradation and is a promising target of acute myeloid leukemia therapy." (PMID 35640380, 2022). "TAK-243 is also undergoing Phase 1 clinical trials in patients with refractory acute myeloid leukemia (AML) to block UBA1, UBA6, and NAE targeted proteins involved in tumor cell division (ClinicalTrials.gov Identifier: NCT03816319)." (PMID 36293188, 2022). "Blocking UBA1 decreased the levels of ubiquitylated proteins, increasing markers of proteotoxic stress and DNA damage stress in acute myeloid leukemia." (PMID 33344241, 2020). "Additionally, UBA1 has been recognized as a potential drug target for acute myeloid leukemia and multiple myeloma." (PMID 39684409, 2024). "In acute myeloid leukemia cells, TAK-243 was seen to attach preferentially with UBA1 over the similar enzymes, UBA2, UBA3, and UBA6." (PMID 34769401, 2021). "We previously reported that acute myeloid leukemia (AML) cell lines and primary patient samples are more dependent on the activity of UBA1 compared with normal hematopoietic cells and thus are more vulnerable to UBA1 inhibition." (PMID 33476303, 2021). "Although UBA1 has been considered as a potential target gene for cancer therapy, especially for acute myeloid leukemia 29, the role of this gene in the pathogenesis of HCC had not been elucidated so far." (PMID 32132870, 2020). "However, the functional mechanism and role of UBA1 in pan‐cancer have not been fully elucidated and its value in haematological tumours (diffuse large B cell lymphoma (DLBC/DLBCL) and acute myeloid leukaemia (AML/LAML)) has not been explored." (PMID 39183260, 2024).